RNU6-1267P (RNA, U6 small nuclear 1267, pseudogene)
Gene: Small nuclear RNA gene on chromosome 17 (30,288,071 to 30,288,177, reverse strand). Ensembl gene ENSG00000222679.
Homologues: Orthologues: chimpanzee U6 (99% identical), macaque U6 (87% identical), pig U6 (77% identical), guinea pig U6 (76% identical), rabbit U6 (72% identical), mouse Gm23337 (63% identical). Paralogues in human: RNU6-434P (78% identical), RNU6-495P (78% identical), RNU6-664P (78% identical), RNU6-698P (78% identical), RNU6-1011P (77% identical), RNU6-1075P (77% identical), RNU6-1117P (77% identical), RNU6-1252P (77% identical), RNU6-1316P (77% identical), RNU6-338P (77% identical), RNU6-38P (77% identical), RNU6-1124P (76% identical), and 1287 more.